LINGO1 (leucine rich repeat and Ig domain containing 1)
Diseases named in the same sentence as LINGO1 in open-access papers (continued):
Sharing a sentence is not in itself a finding about the gene and the disease.
ischemic stroke (2 papers, 2021 to 2024). A stroke disorder caused by obstruction of blood flow to the brain, due to thrombotic (local blood clot formation) or embolic (due to a blood clot or other material traveling from another site) event. "In our present study, we demonstrate that the neuroprotective effect of sh-LINGO-1 in both in vivo and in vitro ischemic stroke models." (PMID 33830473, 2021). "Therefore, we designed this study to determine the effects of LINGO-1 on cerebral I/R injury in vivo ischemic stroke model and in vitro ischemic stroke model." (PMID 33830473, 2021). "LINGO-1 shRNA could ameliorate neurological deficits, reduce brain infarct volume and damage to cerebral cortical neurons in vivo ischemic stroke model, alleviate apoptosis and promote cell proliferation in vitro ischemic stroke model via the NF-κB and JAK2/STAT3 pathway." (PMID 33830473, 2021). "Here, the present study revealed that LINGO-1 shRNA treatment suppressed the activation of the JAK2/STAT3 and NF-κB signaling pathways in both vivo and in vitro ischemic stroke models." (PMID 33830473, 2021).
Obesity (2 papers, 2021). Accumulation of substantial excess body fat. "Four of them, CDIN1 (chr15), LINGO1 (chr15), LINC01184 (chr5), and LOC105369911 (chr12), lie within reported GWAS loci related to BMI, body height, and obesity and are located on different chromosomes from rs12040085." (PMID 33957961, 2021).
optic neuritis (2 papers, 2018 to 2024). Optic neuritis is inflammation of the optic nerve, the nerve that carries the visual signal from the eye to the brain.The conditionmay cause sudden, reduced vision in the affected eye(s). "The past 10 years have seen tremendous progress in both fields as evidenced by the clinical trials evaluating the anti-LINGO1 antibody opicinumab or the antihistamine/anticholinergic drug clemastine for efficacy in MS and optic neuritis (ON), respectively." (PMID 29534752, 2018). "A monoclonal antibody inhibiting LINGO-1 (opicinumab) however showed no clear improvement in phase II trials in MS, or in patients with their first acute optic neuritis incident though it showed improvement in visual evoked potentials." (PMID 38527011, 2024).
Stroke (2 papers, 2012 to 2022). Sudden impairment of blood flow to a part of the brain due to occlusion or rupture of an artery to the brain. "Using real-time RT-PCR of stroke brain tissues, we validated the expression of three selected neuronal genes from the network: Robo3, Lingo1, and NeuroD2, whose expression values were >2 in NPC-CM(M) than in NPC-CM(S)." (PMID 35887140, 2022). "The decreased levels of both LINGO1 and NOGO-A might initially seem to be due to a lower number of OPCs and also OLCs, but the transferrin gene (TF), which is only found in oligodendrocytes in the adult brain, was upregulated at both 24 h and 3 d after stroke." (PMID 23284893, 2012).
tuberous sclerosis (2 papers, 2023). Hereditary disease characterized by seizures, intellectual disability, developmental delay, and skin and ocular lesions. "LINGO-1 also plays an important role in neurological disorders like tuberous sclerosis, focal cortical dysplasia, and TLE, which all include seizures as a common symptom." (PMID 36901909, 2023). "Previous studies showed that both protein and mRNA levels of Nogo-A, NgR, LINGO-1, TROY, and RhoA increased in the cortex of tuberous sclerosis and cortical dysplasia patients." (PMID 36901909, 2023).
cerebral infarction (1 paper, 2011). An ischemic condition of the brain, producing a persistent focal neurological deficit in the area of distribution of the cerebral arteries. "Expression of NgR1, TROY and LINGO-1 was found in CD68+ cells (i.e. macrophages, microglia, and a subset of DCs) within chronic, active demyelinating MS lesions and ischemic lesions of acute and old cerebral infarctions." (PMID 21906273, 2011).
Cerebral ischemia (1 paper, 2021). Restriction of arterial blood supply to the brain associated with insufficient oxygenation to support the metabolic requirements of the tissue. "So far, it is unclear the complicated molecular mechanism of LINGO-1 after cerebral ischemia." (PMID 33830473, 2021). "However, the molecular mechanisms of LINGO-1 engaged in the recovery of nerves after cerebral ischemia still need to be explored." (PMID 33830473, 2021). "LINGO-1 may be involved in the pathogenesis of cerebral ischemia." (PMID 33830473, 2021). "A previous study showed that LINGO-1 might be involved in the pathogenesis of cerebral ischemia." (PMID 33830473, 2021). "This study proved that LINGO-1 was overexpressed in the mouse brain after MCAO and in HT22 cells after OGD/R, which may be one reason for the nerve regeneration disorder after cerebral ischemia." (PMID 33830473, 2021).
cognitive decline (1 paper, 2025). "However, the underlying mechanisms by which Lingo1 regulates cognitive decline after surgery remain to be further elucidated." (PMID 39781463, 2025). "Neurobehavioral experiments revealed that mice with hippocampal neuron-specific Lingo1 overexpression exhibited significant cognitive decline." (PMID 39781463, 2025). "In summary, our study revealed that abnormal Lingo1 upregulation in hippocampal neurons contributed significantly to cognitive decline after unilateral nephrectomy under isoflurane anesthesia by promoting myelin sheath loss or inhibiting myelination." (PMID 39781463, 2025). "Herein, we found that Lingo1 expression was significantly increased in the hippocampal neurons of aged mice after unliteral nephrectomy under isoflurane anesthesia and plays essential roles in the development of cognitive decline." (PMID 39781463, 2025). "To determine the role of Lingo1 in the development of surgery-induced cognitive decline, we artificially upregulated the expression of Lingo1 in hippocampal neurons via stereotaxic microinjection of an adeno-associated virus encoding the full-length mouse Lingo1 gene." (PMID 39781463, 2025). "Moreover, upregulated Lingo1 in hippocampal neurons contributed to cognitive decline after surgery through activating the RhoA/ROCK1 signaling pathway and inhibiting the EGFR/PI3K/Akt signaling pathway." (PMID 39781463, 2025). "Notably, Lingo1 knockdown significantly reversed pathological changes in the hippocampus and attenuated cognitive decline." (PMID 39781463, 2025). "In summary, Lingo1 upregulation in hippocampal neurons might promote myelination inhibition or myelin sheath loss through the RhoA/ROCK1 pathway, which plays important roles in the occurrence and development of postoperative cognitive decline." (PMID 39781463, 2025). "The results demonstrated that Lingo1 was upregulated in both excitatory pyramidal neurons and inhibitory interneurons in hippocampus, suggesting that the dysregulation of Lingo1 expression in all hippocampal neurons might ultimately determine the cognitive decline after surgery in aged mice." (PMID 39781463, 2025). "Moreover, Lingo1 upregulation in hippocampal neurons inhibited the PI3K/Akt signaling pathway by decreasing EGFR levels, which further promoted cognitive decline after anesthesia and surgery by increasing neuronal apoptosis." (PMID 39781463, 2025).
developmental delay (1 paper, 2011). "Overexpression of the LINGO-1 and CSPG4 genes has been implicated in developmental delay seen in other patients with trisomy of 15q24-qter, but our patient is currently too young to ascertain developmental progress." (PMID 23074681, 2011).
Dystonia (1 paper, 2025). An abnormally increased muscular tone that causes fixed abnormal postures. "Among the most significant genetic links are the genes LINGO1, HTRA2, and DNAJC13, which have also been implicated in dystonia." (PMID 40731814, 2025). "Therefore, while LINGO1, HTRA2, and DNAJC13 remain important candidates linking ET, PD, and dystonia, definitive evidence supporting their direct contribution to PD risk is still lacking and requires further investigation." (PMID 40731814, 2025).
glioblastoma (1 paper, 2023). The most malignant astrocytic tumor (WHO grade IV). "LINGO1 was identified as prognostic predicting indicator in primary glioblastoma." (PMID 37237274, 2023).
Hypertension (1 paper, 2023). The presence of chronic increased pressure in the systemic arterial system. "Studies showed that biomarkers include PLD2, FLNA (filamin A), SMURF1, LINGO1, CACNA1H, NLRP6, NLRC3, CXCR2 and C5AR1 plays an important role in progression of hypertension." (PMID 36837510, 2023).
lentivirus infection (1 paper, 2022). Virus diseases caused by the Lentivirus genus. "Reduction in LINGO-1 expression via RNAi lentivirus infection or antagonism via the induced expression of a dominant-negative LINGO-1 variant both promoted the differentiation of cultured oligodendrocytes." (PMID 36555733, 2022).
migraine (1 paper, 2019). "Here we investigated a potential link between migraine and five key Nogo-type signaling genes: RTN4, OMGP, MAG, RTN4R and LINGO1, by screening 15 single nucleotide polymorphisms (SNPs) within these genes." (PMID 31861860, 2019).
ocular hypertension (1 paper, 2016). Abnormally high intraocular pressure. "Lingo1 is able to form a complex with TrkB following ocular hypertension, and it was observed that Lingo1 antagonists caused higher TrkB activation than BDNF alone, leading to the survival of RGCs." (PMID 27555809, 2016). "Blocking Lingo1 function, either using Lingo1-Fc or antibodies against Lingo1, has been shown to not only reduce the number of RGCs that were lost after ocular hypertension, but also promote the survival of RGCs following optic nerve injury." (PMID 27555809, 2016). "Both Lingo1 and NgR were found to be upregulated in RGCs in an ocular hypertension paradigm in rats." (PMID 27555809, 2016).
relapsing-remitting multiple sclerosis (1 paper, 2016). The most common clinical variant of multiple sclerosis, characterized by recurrent acute exacerbations of neurologic dysfunction followed by partial or complete recovery. "This clinical trial by Biogen tested the efficacy and safety of anti-LINGO-1 in patients with relapsing remitting multiple sclerosis (RRMS) or with Secondary progressive multiple sclerosis (SPMS)." (PMID 27595123, 2016).
neurodegenerative disease (4 papers, 2020 to 2025). A disorder of the central nervous system characterized by gradual and progressive loss of neural tissue and neurologic function. "Moreover, the LINGO‐1 gene is related to risk for neuronal apoptosis in patients with neurodegenerative diseases, implying that modulation of myelin inhibitor signaling may promote the survival of neurons and myelination of oligodendrocytes after injury." (PMID 32562344, 2020). "Importantly, its expression is elevated in patients with various degenerative diseases and those with CNS injuries, suggesting the potential pathological role of LINGO‐1 in CNS diseases." (PMID 32562344, 2020).
neurological disorders (4 papers, 2020 to 2025). "Increasing evidence has confirmed that Lingo1 plays substantial roles in regulating brain development and neurological disorders, acting as an important negative regulator of neuronal survival, oligodendrocyte differentiation, axonal regeneration and myelination." (PMID 39781463, 2025). "LINGO-1 expression regulates the timing of central nervous system (CNS) myelination during development, and LINGO-1 upregulation in neurological disorders suggests a deleterious role for the endogenous protein." (PMID 33830473, 2021).
movement disorder (2 papers, 2013 to 2025). Neurological conditions resulting in abnormal voluntary or involuntary movement, which may impact the speed, fluency, quality and ease of movement. "The LINGO1 SNPs analyzed in this study have been studied as putative risk biomarkers for other movement disorders." (PMID 23574883, 2013).
psychiatric disease (2 papers, 2020 to 2025). "Our results also showed that many psychiatric disease-associated remarkable genes, were upregulated (SLC35F1, SNHG5, and FAM118A) or downregulated (SLC26A3, SLC27A4, LINGO1, and RASGEF1B) in PBMCs of patients with WD." (PMID 40384935, 2025). "We identified shared changes in CSF levels of some proteins across two or three major psychiatric disorders including MDD, BI disorder, and SCZ (e.g., NRXN3, CNDP1, LINGO1) indicating shared neuropathology across these diseases." (PMID 32398672, 2020).
tumor (2 papers, 2017 to 2023). "In this perspective, we suggest some options to alleviate this risk that can make targeting tumour cells expressing the LINGO-1 antigen a safe option." (PMID 30613826, 2017). "We found that most genes with hazard ratio > 1 (GPRASP1, APLP1, ALPK3, SPTBN5, PCDHB14, LZTS3 and RGL2) have a higher expression in tumor tissues than normal tissues except LINGO1 and LZTS1." (PMID 37237274, 2023). "Strategic development of LINGO-1 targeted delivery vehicles can deliver drugs or macrodrugs specifically to EWS tumour cells sparing the normal body tissues." (PMID 30613826, 2017). "Some or all of these have potential to be guided to tumour locations by anti-LINGO-1 antibody (or antibody fragment) coating." (PMID 30613826, 2017).
brain disorder (1 paper, 2015). A disease affecting the brain or part of the brain. "In addition, there appear to be many regulatory elements that potentially regulate expression of neural-expressed genes involved in brain disorders (for example, Parkin2, Lingo1, Dscam, Msra)." (PMID 25972927, 2015).
central nervous system disorder (1 paper, 2025). A disease involving the central nervous system. "Numerous studies have shown that endogenous Lingo1 plays critical roles in negatively regulating the EGFR/PI3K/Akt signaling pathway in the pathophysiology of central nervous system disorders by reducing EGFR levels through direct physical interactions." (PMID 39781463, 2025). "The RhoA/ROCK signaling pathway plays crucial roles in many central nervous system disorders as an important downstream pathway of Lingo1." (PMID 39781463, 2025).
retinopathy (1 paper, 2020). "Our results showed that the expression pattern of SP1 paralleled that of LINGO‐1 in ONC‐injured RGCs, further implying that SP1 may regulate LINGO‐1 in retinopathy." (PMID 32562344, 2020).
LINGO1 also shares sentences with these, for which no sentence is quoted: schizophrenia (4 papers); autism spectrum disorder (2); cancer (2); diabetes (2); Parkinson (2); allergic rhinitis (1); amyloid (1); Anxiety (1); asthma (1); attention deficit-hyperactivity disorder (1); autoimmune disease (1); deafness (1); dementia (1); eczema (1); encephalomyelitis (1); glioma (1); ischemia (1); memory impairment (1); microcephaly (1); mood disorder (1); multiple myeloma (1); neurodevelopmental disorder (1); of the CNS (1); prostate carcinoma (1); rheumatoid arthritis (1); secondary progressive multiple sclerosis (1); Seizure (1); Tremor (1); type 2 diabetes mellitus (1); West syndrome (1).